STAT3 (signal transducer and activator of transcription 3)
Diseases named in the same sentence as STAT3 in open-access papers (continued):
Sharing a sentence is not in itself a finding about the gene and the disease.
tumor (continued). "It has also been reported that STAT3 controls the malignant behavior of tumor cells, while it dictates the responsiveness to radio- and chemotherapy." (PMID 36509291, 2022). "A number of studies have indicated that the excessive activation of STAT3 can prevent tumor cells from undergoing apoptosis and facilitate cell proliferation, invasion, and migration." (PMID 36042375, 2022). "Since PD-L1 is a target gene of STAT3, we expected that inhibition of STAT3 in tumor acidosis would inhibit the expression of PD-L1." (PMID 35927628, 2022). "Cross‐regulation is particularly evident in cancer cells where the deletion of STAT1 or STAT3 alters the expression of genes controlling tumour expansion and proliferative survival." (PMID 34618359, 2022). "In this study, we elucidated that when cultured on the newly revised PTF platform, polymer X, the STAT3 signaling pathway was activated to obtain CSC-like properties in tumor cells." (PMID 36359204, 2022). "Inflammatory cells produce tumor necrosis factor α, transforming growth factor β, interleukin-6, and other cytokines, and these inflammatory agents regulate nuclear factor (NF)-κβ and the STAT3 pathway and encourage metastasis in tumor cells." (PMID 35387666, 2022). "In vitro, the inhibition of STAT3 suppresses M2 polarization and tumor cell proliferation in human GBM cells." (PMID 35267626, 2022). "STAT3 signalling molecules hinder the conversion of cold to hot tumours by regulating immunosuppressive molecule secretion and immunosuppressive cell functions." (PMID 35665592, 2022). "This is the first evidence, to the best of our knowledge, that an intrinsic immunosuppressive pathway (IL-6/STAT3) can directly affect tumor antigenicity leading to changes in the T-cell lymphocyte repertoire and restrict antigen dependent tumor immunity." (PMID 36443756, 2022). "STAT3 is upregulated in GBM in hypoxic conditions, resulting in increased expression of vascular endothelial growth factor (VEGF) and hypoxic inducible factor-1 (HIF-1), and STAT3 has been noted to be critical in maintaining tumor stem cells." (PMID 35203636, 2022). "The IL6/JAK/STAT3 signaling pathway plays an essential role in the proliferation, survival, and invasion of tumor cells." (PMID 35799780, 2022). "STAT3 is the most commonly activated transcription factor in tumors where it regulates processes characteristic of tumor cells such as uncontrolled proliferation, resistance to apoptosis, angiogenesis, and immune response escape." (PMID 35897737, 2022). "NKILA is a tumor suppressor that affects the proliferation and metastasis of cancer cells by regulating the STAT3 pathway." (PMID 35368654, 2022). "HSP72 and HSP105 on the TEX surface were found to induce DCs to produce increased IL-6 in a TLR2- and TLR4-dependent manner, which in turn promoted tumor invasion by increasing STAT3-dependent matrix metalloproteinases 9 transcription activity in tumor cells." (PMID 35163380, 2022). "Several studies confirmed that tumor-supporting effect of CD163+ TAMs is mediated by the activation of STAT3 signaling pathway." (PMID 36686729, 2022). "Still, other work suggests that STAT3 functions as a tumor suppressor in lung tumor initiation but behaves as an oncogene in established tumors." (PMID 35406557, 2022). "Different pharmacological approaches able to counteract STAT3 hyperactivation induce the growth arrest and apoptosis of tumor cells in vitro as well as tumor regression in vivo, validating STAT3 as an anticancer target to be exploited in drug discovery." (PMID 35956786, 2022). "IL-6 is a well-established tumor-promoting cytokine among the IL-6 family of cytokines, which activates multiple STAT3-mediated tumor initiation and progression pathways." (PMID 36010693, 2022). "High VEGF-A levels strongly correlated with both STAT3 and Myc expression as well as with tumor metastatic potential." (PMID 35351947, 2022).
tumor (continued). "Under normal physiological conditions, STAT3 activation can only be maintained for a short time, whereas STAT3 is continuously activated in various tumor cells." (PMID 35252007, 2022). "The azetidine-based small molecules are a new class of inhibitors that potently and irreversibly bind to Stat3, leading to tumor cell death and tumor growth inhibition in vivo." (PMID 35276290, 2022). "Mechanistically, the inhibition of STAT3Y705 phosphorylation in tumor tissues confirmed again anti-tumorigenic effects of Stattic by antagonizing STAT3 activity." (PMID 35288541, 2022). "STAT3 degradation is expected to inhibit the tumor immune evasion and combine with the anti–PD-L1 antibody for immunotherapy." (PMID 36509291, 2022). "Given that disruption of STAT3‐dimerizaton is a potential and effective anti‐cancer target, these results indicate that the tumor suppression action of SHF is mechanically targeted toward STAT3 dimerization." (PMID 35843865, 2022). "As a member of the STAT family, STAT3 is considered the main mediator of tumorigenesis and plays an important role in the proliferation, invasion, and angiogenesis of tumor cells." (PMID 36225196, 2022). "RNF7 overexpression inhibited apoptosis and promoted glycolysis in vitro and increased tumor growth in vivo by activating the JAK/STAT3 signaling pathway by ubiquitination of SOCS1." (PMID 35562668, 2022). "This is the first research that discovered effective STAT3 inhibitors as potent anti-tumour agents from celastrol derivatives." (PMID 34894961, 2022). "In the subcutaneous homograft and liver orthotopic transplantation mouse models of Hepa1‐6 cells, the inhibitor of STAT3 napabucasin effectively suppressed tumour growth and prolonged the survival of HCC mice." (PMID 35665592, 2022). "STAT3 is important in tumor cell survival, and there is growing interest in targeting STAT3 to induce cancer cell apoptosis." (PMID 35562668, 2022). "Tumor cell-derived GM-CSF promotes Sp1 binding to the FCGR2B promoter to increase the expression of FcγRIIB that subsequently activates the Stat3 signaling pathway to promote generation of gMDSCs in the TME." (PMID 34976216, 2022). "Both mice and human tumors incubated with reactive T cells had elevated their p-STAT3 levels, in comparison to untreated tumor cells, suggesting this mechanism is conserved across species." (PMID 36124553, 2022). "Within these diverse subtypes, STAT3 signaling is a crucial factor that skews T cells towards pro-tumor Th17 and Treg immunity while also increasing PD-L1 expression, yielding functional exhaustion." (PMID 35406557, 2022). "Studies have shown that STAT3 has a crucial role in stromal cells, including immune cells, which are recruited to the tumor microenvironment to promote tumor progression." (PMID 36582521, 2022). "Kaplan-Meier univariate analysis showed that tumor differentiation, pN, pTNM, and p-STAT3 were the related factors affecting the 5-year survival rate of AEG patients." (PMID 36225196, 2022). "Stat3 signaling contributes to tumor cell survival, proliferation, migration, invasion, and chemoresistance, as well as influencing angiogenesis, immunosuppression, and cancer stem cell (CSC) self-renewal/differentiation." (PMID 36017196, 2022). "Macrophages express IL-6, TNF-alpha, and cathepsin B to activate STAT3 pathways in tumor cells, which increases the proliferation and survival of cancer cells treated with various chemotherapeutics." (PMID 35183252, 2022). "Previously, miR-26a was shown to suppress tumor growth and metastasis formation by targeting the IL-6/STAT3 pathway and modulate the neuroinflammatory response induced by TLR4 stimulation." (PMID 36499093, 2022). "Inhibition of STAT3 expression in tumor cells can slow down the progression of cancer and block tumor growth and tumor cell migration." (PMID 36340269, 2022).
tumor (continued). "The intracellular expression of FABP4 in macrophages downregulates miR-29b via enhanced activation of NF-κB, which negatively regulates the IL-6/STAT3 signaling pathway and leads to subsequent tumor colony formation." (PMID 36060264, 2022). "IL-17 can promote the activation of the STAT3 signal transduction pathway through the intermediate mediator IL-6 in tumor cells." (PMID 36544490, 2022). "In this study, we found for the first time that PELP1 was positively correlated with MVD in CRC and proved that PELP1 regulated tumor angiogenesis through the STAT3/VEGFA axis." (PMID 35053547, 2022). "An additional type of cluster interaction that was significantly higher within the tumor area of brain metastases involves CD3+p-STAT3– T cells with both CD163+p-STAT3– macrophages and CD11c+CD163+p-STAT3– cells (P = 0.018)." (PMID 35316217, 2022). "The overexpression of CD45 protein tyrosine phosphatase (PTP) in MDSCs exposed to hypoxia in the tumor site promotes the inactivation of STAT3, resulting in the M-MDSC differentiation to TAM." (PMID 35565420, 2022). "Collectively, these in vivo findings show that Stattic suppressed PC growth in a nude mouse tumor model by inactivating STAT3." (PMID 35288541, 2022). "Treatment with the small-molecule STAT3 inhibitor CPA7 boosts anti-tumor responses against the subcutaneously injected urothelial carcinoma cell line MB49, which is largely dependent on T cells with a partial involvement of NK cells." (PMID 35865518, 2022). "IL6 receptor blockade suppresses STAT3 phosphorylation in both myeloid cells and tumor cells, thus sensitizing tumor cells to gemcitabine." (PMID 36230914, 2022). "Activators of transcription (STAT3) mediates the signal transduction of HIF-1α to stimulate tumor growth and maintain the invasive ability of EC cells." (PMID 35800058, 2022). "As a point of convergence for numerous oncogenic signaling pathways, excessive STAT3 activation within cancer cells can be viewed as a neoplastic mimic of an inflammation-driven repair response that collectively promotes tumor progression." (PMID 36266267, 2022). "For example, STAT3 regulates the expression of vascular endothelial growth factor (VEGF) and is associated with angiogenesis and tumor progression." (PMID 35314590, 2022). "Phosphorylated STAT3 (pSTAT3Tyr705) dimerizes and translocates to the nucleus, where it activates its target genes leading to proliferation, survival, and tumor invasion." (PMID 35267609, 2022). "Ovarian mesenchymal stem cells (OvMSCs) secrete IL-6 and SKOV3 cells exposed to this conditioned media, resulting in enhanced tumor sphere formation and activation of STAT3." (PMID 36550571, 2022). "A considerable amount of literature has demonstrated that JAK/STAT3 pathway is extensively involved in tumor progression." (PMID 35501324, 2022). "Consistent with the function of STAT3 in vitro, inhibition of STAT3 by Stattic largely eliminated the enhancement in tumor growth induced by SHC4 overexpression." (PMID 35033067, 2022). "Some studies have shown that IL-6 is involved in increasing the proliferation of tumor cells in colon and NFκB/IL-6/STAT3 signaling seems to play a crucial role in CAC development." (PMID 35410210, 2022). "Collectively, our study demonstrates that miR-21 provides an important signaling node downstream of Stat3 to confer tumor-cell-intrinsic cancer hallmarks, and therefore identifies miR-21 expression as a therapeutic cancer vulnerability." (PMID 35053428, 2022). "In hepatocellular carcinomas, constitutive activation of STAT3 stimulates cell proliferation and tumor angiogenesis, decreasing apoptosis and antitumor immunity." (PMID 35806366, 2022). "In order to explore the mechanism of RT against tumor invasion and metastasis, we detected the effects of RT on the expressions of STAT3, p-STAT3, and Nrf2 in B16F10 cells by Western blots and qPCR." (PMID 36014573, 2022).
tumor (continued). "Overall, this study indicates that celastrol inhibits tumor angiogenesis by suppressing mitochondrial function and morphology via the STAT3/OPA1/P65 pathway and provides new insight for mitochondrion-targeted cancer therapy." (PMID 36678677, 2022). "Of particular interest is the IL‐6/JAK/STAT3 pathway, which is known to drive tumor proliferation, survival, and even metastasis." (PMID 36176603, 2022). "Aberrantly activated STAT3 can induce immunosuppression by regulating crosstalk between tumor cells and immune cells in the tumor microenvironment." (PMID 36551618, 2022). "FOXD2-AS1 is complexed as a scaffold with STAT3 and PRMT5, stimulating the transcription STAT3, which is important for maintaining tumor stemness and enabling chemotherapeutic resistance." (PMID 36359888, 2022). "Antibiotic chemotherapeutics induce GSDMC-mediated pyroptosis in hypoxic tumor environments by upregulating the nPD-L1/pro-signal transducer and activator of transcription 3 (p-STAT3) complex." (PMID 36091247, 2022). "HIF-1α is essential for lactate-mediated activation of GPR81/mTOR/HIF-1α/STAT3 pathway, and inhibition of lactate production in tumor cells or HIF-1α expression in MDSC can restore the immune response of antitumor T cells." (PMID 36686771, 2022). "The Ref-1/HIF-1α/STAT3/NF-κB signaling node likely contributes to disease attributes linked to TSC pathology, such as inflammation, cell migration/invasion, tumor growth, metabolic transformation, and angiogenesis." (PMID 36551683, 2022). "Aberrantly-active Stat3 promotes tumor cell growth and proliferation, survival, migration, invasion, and metastasis." (PMID 35276290, 2022). "In CRC, circHIPK3/miR-637/STAT3 axis is associated with lower OS and DFS, larger tumor volume, higher probability of regional lymph node metastasis, distant metastases, and poor recovery." (PMID 36175921, 2022). "In MDA-MB-231 cell xenografted nude mice, knockdown of cirRHOT1 can increase the expression of miR-106a-5p in tumor tissue, while reduce the expression of STAT3, and the tumor growth is significantly inhibited." (PMID 36408273, 2022). "Among many other immunosuppressive mechanisms, STAT3 aids tumor cells to escape natural killer (NK) cell-mediated immune surveillance." (PMID 35865518, 2022). "Patients with a large percentage of p‐STAT3 positive tumor cells had shorter progression‐free survival years and overall survival years." (PMID 35356799, 2022). "MDSCs induce the EMT program by releasing various cytokines, such as PGE2, TGFβ, EGF, and HGF, and strengthen the tumor stemness using IL6 that activates STAT3 and NOTCH pathways." (PMID 36211375, 2022). "Li and coworkers demonstrated that FLU inhibited the tumoral expression of PD-1, but not PD-L1, and the effect was concomitant to a drug-induced down-regulation of phospho-STAT3 in the tumor tissue." (PMID 35884428, 2022). "Taken together, TSM-1 inhibited tumor growth by reducing STAT3 protein levels and suppressing its downstream signaling pathways." (PMID 36509291, 2022). "Taken together, these results indicated that OCLN controls tumour angiogenesis by regulating p‐STAT3 levels in BLCA cells through effects on IL8 expression." (PMID 35224833, 2022). "The results suggest that a bifunctional combination has the potential to disrupt the tumor immunological escape mediated by STAT3." (PMID 36230984, 2022). "Bazedoxifene also reduces TNBC tumor volume suggesting the translational potential of the compound as an IL-6/JAK/STAT3 inhibitor." (PMID 35371975, 2022). "Previous study reported that STAT3 in tumor microenvironment can reduce the activity of NK cells to help tumors evade immune recognition." (PMID 36295083, 2022). "The sustained activation of STAT3 increases the tumor cell proliferation, survival, and invasion, thereby accelerating the tumor formation process." (PMID 36014805, 2022). "Tumor cell proliferation in the bone was also reduced after STAT3 knockdown, abolishing the proproliferation effect of IL20RB." (PMID 36006737, 2022).
tumor (continued). "The results revealed that the downregulation of PAQR5 enriched mainly the gene set related to the upregulation of STAT3 targets, tumor formation, and poor tumor differentiation and enriched the gene set of downregulated tumor metastasis and NRAS signaling." (PMID 36119517, 2022). "Several studies have indicated that STAT3 knockout or the use of miR-124 reduces Treg cells while increasing anti-tumor activity in the GBM animal model." (PMID 35954362, 2022). "SYF regulates the expression of genes involved in cell proliferation, migration, and invasion by regulating the JAK/STAT3 signalling pathway and finally inhibits tumour cell metastasis in TNBC." (PMID 36678509, 2022). "Although S3I-201, a STAT3 inhibitor, inhibited cell proliferation, CUEDC2 knockdown did not reduce cell proliferation in S3I-201 treated tumor cells, confirming that CUEDC2 inhibits tumor cell growth through a STAT3-independent manner." (PMID 36231027, 2022). "In the process of chronic inflammation promoting tumor development, the STAT3 activity of cells can be significantly increased under the stimulation of inflammatory factors such as IL-6, thereby upregulating the expression of cyclins and oncoproteins." (PMID 36188592, 2022). "The hypoxic microenvironment around tumors induces CNS macrophages to become TAMs, which subsequently adopt a tumor-supportive phenotype (M2 macrophages), and this process is mediated by the STAT3 pathway." (PMID 35203636, 2022). "In contrast, depletion of STAT3 or combination with ruxolitinib led to tumor regression upon treatment with neratinib." (PMID 35729402, 2022). "Activation of both the NFκB and STAT3 pathways enhance the expansion and accumulation of MDSCs in the tumor." (PMID 35697801, 2022). "The STAT3 signal pathway is the major intrinsic pathway for tumor-promoting inflammation, and has a key role in the impairment of anti-tumor immunity." (PMID 35205801, 2022). "Elevated IL-6 can stimulate the excessive activation of STAT3, including angiogenesis and tumor metastasis." (PMID 35672352, 2022). "The dysfunctional regulation of the STAT3 oncogene contributes to tumor development and progression in several cancers, including HNSCC." (PMID 35890129, 2022). "IL-6/JAK2/STAT3 pathway has considerable potential in inhibiting tumor growth and restoring anti-tumor immunity." (PMID 36591515, 2022). "Since SHF is a protein containing a SH2 domain, we sought to determine the involvement of the SH2 domain in mediating STAT3 dimerization inhibition and tumor suppression." (PMID 35843865, 2022). "Conversely, aberrant and persistent activation of STAT3 was observed in both tumor cells and adjacent stromal and immune cells." (PMID 35836213, 2022). "VEGF-A promoted tumor cell self-renewal through VEGF-A/VEGF-R/STAT3 signaling resulting in activation of Myc, Sox2 and STAT351–53." (PMID 35351947, 2022). "In sporadic gastrointestinal cancers, the IL-11/STAT3 signalling axis is a powerful tumour progressor." (PMID 36615513, 2022). "Interaction between NF-κB and STAT3 in tumor microenvironment is known to increase tumors promoting inflammation and pro-tumor signaling to be polarized the M2 macrophage phenotype." (PMID 35890318, 2022). "In the tumor microenvironment, the Jak/STAT3 signaling pathway drives tumor cell proliferation, survival, invasion, and metastasis, and suppresses anti-tumor-related immune responses." (PMID 36175921, 2022). "Multiple cell types in the tumour microenvironment, such as TAMs, granulocytes and fibroblasts, produce IL‐6, leading to JAK/STAT3 signalling activation in tumour cells that promotes cell proliferation, survival, invasiveness and metastasis." (PMID 35363937, 2022).